BASP1P1 (BASP1 pseudogene 1)
Gene: Processed pseudogene on chromosome 13 (22,897,341 to 22,898,005, reverse strand). Ensembl gene ENSG00000230535.
Diseases named in the same sentence as BASP1P1 in open-access papers:
BASP1P1 is named in the same sentence as 1 disease in open-access papers, as found by Europe PMC text mining. Sharing a sentence is not in itself a finding about the gene and the disease. The quoted sentences say what the papers report.
cancer (1 paper, 2023). A tumor composed of atypical neoplastic, often pleomorphic cells that invade other tissues. "In contrast, the BASP1P1 locus demonstrated significantly lower methylation in all cancer patients at all time points." (PMID 36611168, 2023).